SLC7A5 (solute carrier family 7 member 5)
Diseases named in the same sentence as SLC7A5 in open-access papers (continued):
Sharing a sentence is not in itself a finding about the gene and the disease.
tumor (continued). "The solute carrier L-type amino acid transporter 1 (LAT-1/SLC7A5) is a viable target for drug delivery to the central nervous system (CNS) and tumors due to its high abundance at the blood–brain barrier and in tumor tissue." (PMID 35408997, 2022). "Since SLC7A5 is up-regulated both in PDAC tissue and muscle of PDAC patients, fold-change (relative to normal counterparts) of SLC7A5 expression in muscle and tumor was calculated to determine which one potentially acquires more BCAAs from circulation." (PMID 33882453, 2021). "The level of SLC7A5 expression significantly correlates with (18F)fluciclovine uptake by tumor tissues in patients with hormone naïve PCa, and tumors with high Gleason grade have higher SLC7A5 expression and 18F-fluciclovine signal." (PMID 33401748, 2021). "When SLC7A5 SE was repressed, tumor growth also showed a trend of reduction, but the difference was not significant enough." (PMID 34737287, 2021). "For other genes, AURKA, PTTG1, CDC20, SLC7A5, E2F8, TPX2, and TUBA4A, high expression in the high-risk group was linked to tumour growth and metastasis." (PMID 34131308, 2021). "Another study demonstrated that in tumor cells SLC7A5 can regulate the expression of c-MYC, forming a mechanism that connects essential amino acid transport and tumorigenesis." (PMID 34977008, 2021). "Here, we found that tumor-bearing caused an increase in the plasma glutamine level and tumor expression of SLC1A5, SLC7A5, and that glutaminase was further elevated in obese mice." (PMID 32121098, 2020). "Results were consistent with SLC7A5/SLC3A2 mRNA expression whereby patients with SLC7A5+SLC3A2+ tumours had a worse outcome compared to patients of other subgroups." (PMID 32093034, 2020). "Our results indicated that high co-expression of the SLC7A5/SLC3A2 complex is associated with poor prognostic clinicopathological parameters, including a larger tumour size, higher grade, poor NPI and vascular invasion." (PMID 32093034, 2020). "Solute carrier family 1 member 5 (SLC1A5) and solute carrier family 7 member 5 (SLC7A5) are two key amino acid transporters that have been attracting attention due to their role in supporting tumour metabolism." (PMID 31819174, 2020). "Slc7a5 upregulation has also been reported in a variety of tumor types, and Slc7a5 inhibition attenuates proliferation of cells." (PMID 33164746, 2020). "Several studies have shown that miR-126 targets include ADAM9, LRP6, PIK3R2, CXCR4, and SLC7A5, all of which participate in the development of diverse tumor types." (PMID 32554852, 2020). "Lat1 (SLC7A5) is an amino acid transporter often required for the import of essential amino acids, including methionine, in tumor cells." (PMID 32448308, 2020). "Of relevance here, it was demonstrated that HIF-2α binds to the SLC7A5 proximal promoter through its DNA binding domain, and it therefore contributes to SLC7A5′s gene expression in tumor cells, and under hypoxic conditions." (PMID 32715162, 2020). "The importance of the current findings stem from the inherent resistance of RB to chemotherapy and the recent attention given to SLC7A5 inhibition, which has been reported with the potential to inhibit tumor growth and metastasis both in vitro and in vivo." (PMID 31803607, 2019). "Although targeting inhibition of SLC7A5/mTORC1 pathway enhances chemosensitivity of tumor cells, the role of SLC7A5 in cell cycle progression is still unclear." (PMID 31803607, 2019). "The L-type Amino acid Transporter (LAT1, SLC7A5) represents a promising drug target responsible for nutrient uptake, brain drug delivery, and tumor growth." (PMID 31636293, 2019). "Pharmacological blockade of SLC1A5 and SLC7A5 using a newly designed small molecule antagonist, V-9302, elicited a marked anti-tumor response in pre-clinical tumor models." (PMID 31652923, 2019). "Taken together, these findings suggest that miR-184 performs tumor-suppressive roles and enhances chemosensitivity via directly targeting SLC7A5." (PMID 31803607, 2019).
tumor (continued). "SLC7A5 mRNA and protein expression were strongly correlated with larger tumour size and higher grade." (PMID 29566741, 2018). "Even though the consequences of blocking SLC7A5 in the highly proliferative ER+ tumours remain undetermined, this study suggests that SLC7A5 can potentially be used as a therapeutic target for luminal B BC." (PMID 29566741, 2018). "This study has revealed for the first time that SLC7A5 is a key amino acid transporter in the more aggressive and highly proliferative ER+ tumours." (PMID 29566741, 2018). "Among all BC subtypes, SLC7A5 protein expression was an independent predictor of short BCSS in ER+ high-proliferation tumours only." (PMID 29566741, 2018). "There was lower expression of SLC7A5 protein in the low-proliferation tumours than in the other defined molecular subtypes subtypes (p < 0.001)." (PMID 29566741, 2018). "Slc7a5 transcription was increasing with tumor progression from wild-type to BRAFV600E single-mutant tumors, which correspond to benign and PTC lesions, and BRAFV600E/PIK3CAH1047R double-mutant tumors that consisted of PTC and ATC foci." (PMID 30241549, 2018). "There was a positive relationship between SLC7A5 and MYC, mTOR and ATF4 (p < 0.001) and the positive relationship between MYC, HIF2A and SLC7A5 was only observed in luminal B tumours (p = 0.01 and p < 0.001, respectively)." (PMID 29566741, 2018). "Analysis of the expression of both CRKL and SLC7A5 in 72 tumor specimens by IHC was conducted, compared with the adjacent non-cancerous tissues." (PMID 27846244, 2016). "Patients with high correlated expression of either CRKL or SLC7A5 in tumor tissue showed a significant tendency towards poor prognosis and high mortality (P<0.05)." (PMID 27846244, 2016). "A previous study revealed the upregulation of SLC7A5 in many human primary tumors possibly because of the constant, high demand for nutrients in tumor cells." (PMID 26657287, 2016). "With intensive studies on SLC7A5, we further discovered that SLC7A5 is one of the targeted genes of microRNA-126 (miR-126), a pivotal post-transcriptional tumor suppressing microRNA in GC, by using dual-luciferase reporter assay." (PMID 27846244, 2016). "We also found that c‐Myc overexpression elevated SLC1A5/SLC3A2/SLC7A5 expression in RTN4IP1‐deficient cells, and promoted cell proliferation as well as tumor growth upon RTN4IP1 knockdown, demonstrating the essential role of SLC1A5/SLC3A2/SLC7A5 in RTN4IP1‐mediated cell proliferation." (PMID 39757767, 2025). "Moreover, remarkable upregulation of SLC1A5, SLC3A2, and SLC7A5 were revealed by Western blotting in paired ESCC tumor and normal tissues." (PMID 39757767, 2025). "Furthermore, we evaluated the effect of the simultaneous knockdown of SLC1A5, SLC3A2, and SLC7A5 on tumor growth in a cell‐derived xenograft (CDX) mouse model." (PMID 39757767, 2025). "The results showed that SLC1A5/SLC3A2/SLC7A5 knockdown diminished tumor growth in vivo." (PMID 39757767, 2025). "Furthermore, in vivo experiments showed that combined sh-SLC7A5 and oxaliplatin treatment more effectively suppressed tumor growth compared to treatment with oxaliplatin alone." (PMID 40133832, 2025). "If essential amino acids drop tenfold similar to glucose, IDO1 in the tumor environment could elevate Kyn tenfold, reaching the competitive level for SLC7A5 and effectively activating AhR." (PMID 40103267, 2025). "CAFs deliver METTL3 to NSCLC cells, upregulating SLC7A5 expression, modulating tumor cell behavior." (PMID 40740874, 2025). "In KIRC and LGG, the higher the malignancy of tumor, the higher the expression of SLC7A5." (PMID 38790003, 2024). "Glutamine is exchanged with essential amino acids, including leucine, via SLC7A5 in tumor cells." (PMID 38172980, 2024). "Intestinal epithelial deletion of Slc7a5 significantly delays tumor proliferation." (PMID 39465140, 2024).
tumor (continued). "MRPL35 expression was stabilized by USP39‐induced deubiquitination in NSCLC cells, and knockdown of MRPL35 suppressed NSCLC cell proliferation, invasion, and glutamine metabolism in vitro and impeded tumor growth in vivo by upregulating SLC7A5, providing a promising therapeutic target for NSCLC." (PMID 38987867, 2024). "In addition, HIF-2 induces the expression of Gln transporter SLC7A5 and activation of mTORC1, leading to cell proliferation and tumor growth." (PMID 39199642, 2024). "In addition, the anti-tumor efficacy of CAR-T was significantly enhanced when co-cultured with SLC7A5 knockdown LUSC cells at low Met concentration." (PMID 38182561, 2024). "Notably, the expression of the SLC7A5 gene exhibited significant differences (Kruskal–Wallis test, p = 8.2 × 10−20): elevated expression was observed in tumor samples compared to normal tissues, with a further increase in metastases relative to tumors." (PMID 38256136, 2024). "Moreover, previous studies have shown that SLC7A5 is important for the growth and proliferation of tumor cells." (PMID 37731509, 2023). "Overexpression of SLC7A5 has been widely observed in tumor tissues." (PMID 37731509, 2023). "When separated into tertiles according to SLC7A5 tumor expression, we found that patients with elevated SLC7A5 had worse overall survival than patients with low levels, supporting a relationship between neutral amino acid uptake—including methionine—and tumor progression." (PMID 37318751, 2023). "One specific gene identified as upregulated in the tumor infiltrating NK population was SLC7A5." (PMID 35874727, 2022). "However, we found reduced activity of the amino acid transporter SLC7A5 in tumor-infiltrating CD8 T cells of obese mice." (PMID 35103755, 2022). "Then, the expression levels of ZNF24 and SLC7A5 were detected in 16 selected KRAS mutation tumor tissues and KRAS wild-type tumor tissues from the samples by qPCR and Western blot analysis, and we found that the expression levels of ZNF24 and SLC7A5 were both increased in KRAS mutation patients." (PMID 36505791, 2022). "In addition, knockdown of ZNF24 reduced ki-67 positive cells in transplanted tumors, while SLC7A5 overexpression after ZNF24 knockdown partially reversed tumor suppression, and ki-67 positive cells were increased." (PMID 36505791, 2022). "Finally, YAP1 and TAZ, downstream effector proteins of the Hippo tumor suppressor pathway, are also examples of proteins that upregulate SLC7A5 expression." (PMID 33953707, 2021). "Moreover, tumours with high SLC38A2 expression were also commonly represented in the poor prognostic high SLC cluster (SLC1A5+/SLC7A5+/SLC3A2+)." (PMID 33028955, 2021). "In addition, SLC7A5 deletion in human colon, lung, and kidney cancer cell lines resulted in mTORC1 inhibition leading to tumor growth arrest in vitro and in vivo." (PMID 33953707, 2021). "Interestingly, SLC3A2 deletion in the same cell types showed intact mTORC1 activity and tumor growth rate, but the cells were sensitive to SLC7A5 inhibition via treatment with JPH203." (PMID 33953707, 2021). "Furthermore, circZNF124 absence decreased the number of Ki67‐positive Ishikawa cells and downregulated SLC7A5 protein expression in the neoplasms from sh‐circZNF124 group when compared with its expression in those tissues from sh‐NC group." (PMID 34145797, 2021). "Manipulating such therapies to increase SLC1A5, SLC3A2, and SLC7A5 expression in the immune cells could enhance anti-tumor immunotherapy and lead to developments in the field." (PMID 33953707, 2021). "First, we used the METABRIC cohort to investigate the possible correlation between mRNA and clinical outcome; this analysis revealed that patients with SLC7A5+SLC3A2+ tumours had a significantly worse recurrence, distant metastasis and shorter survival (p = 0.01) compared to other subgroups." (PMID 32093034, 2020). "Likewise, many SLC7A5-related tumor studies have demonstrated a critical role of SLC7A5 in tumor migration and invasion." (PMID 32867828, 2020).
tumor (continued). "Along this line, higher expression of CaIX, Phd3, Slc7a5, Glut1, Pgm1 occurred but not Ndrg1 in a Vhl-deficient renal cell mouse model when compared with non-tumor renal region, which is in line with our data in Vhl-deficient kidneys." (PMID 33321829, 2020). "Overexpression of SLC7A5 has been observed in a wide range of tumor cells." (PMID 31803607, 2019). "In addition, miR-6775-3p also directly inhibits its host gene SLC7A5 which has been found to function as an oncogene in tumor progression." (PMID 30333480, 2018). "SLC7A5 is involved in the growth and mortality of a variety of tumor cells." (PMID 30558624, 2018). "A previous study showed that activation of the HIF2α pathway increases mTORC1 activity by upregulating expression of the amino acid carrier SLC7A5 and the current study confirmed the positive correlation between HIF2α and SLC7A5, which was only observed in luminal B tumours." (PMID 29566741, 2018). "Functional coupling of SLC1A5 and SLC7A5 was observed in HeLa cells by transport and efflux of extracellular glutamine as a substrate for leucine uptake and mTOR activation, which are important for tumor cell growth." (PMID 29562706, 2018). "However, in these subtypes the significant association between SLC7A5 protein expression and patient outcome was only observed in the HER2+ tumours." (PMID 29566741, 2018). "However, SLC7A5-selective inhibitor JPH203 has been shown to induce growth inhibition of tumor cells in different human cell lines and mouse models." (PMID 29562706, 2018). "In addition, miR-6775-3p functions as a tumor suppressive miRNA through in part through inhibiting its host gene SLC7A5." (PMID 30333480, 2018). "Interestingly, the functional coupling of SLC1A5 and SLC7A5 glutamine transporters suggests that enhanced glutamine metabolism in tumor cells can contribute to drive tumor growth through activation of mTOR." (PMID 28040803, 2016). "Therefore, SLC7A5 is responsible for tumor progression and immune escape driven by ALYREF." (PMID 38402198, 2024). "Also, SLC7A5 silencing diminishes proliferation and migration in tumor." (PMID 38705513, 2024). "In addition, since the upregulation of SLC7A5 is closely related to abnormal amino acid metabolism and immune evasion, in this study, we identified the regulatory mechanism of ZNF24 on SLC7A5, which is crucial for the blockade of tumor metabolism and immunotherapy of KRAS mutant LUAD." (PMID 36505791, 2022). "Additionally, the SLC7A5 gene plays an important role in promoting tumor development." (PMID 36292783, 2022). "Molecular studies further determined that enforced miR-184 plays tumor-suppressive roles in RB cells and enhances chemosensitivity via enhancing G2/M phase arrest and cellular apoptosis mediated through directly targeting SLC7A5 and its downstream ATR/ATM pathway." (PMID 31803607, 2019). "Overall, our study highlights the reduced dietary L-Leu intake as a promising therapeutic strategy to control SLC7A5-mediated T cell expansion and GVHD and reduce tumor growth while preserving the GVT response." (PMID 40399490, 2025). "SLC7A5 was significantly overexpressed in early-stage (stages I and II) CRC cases, although it was less prevalent in tumours with mucinous histology and those exhibiting lymphovascular invasion in IHC staining." (PMID 41154605, 2025). "As an important tumor suppressor gene, the mechanism by which ARID1A affects the expression of SLC7A5 will also be a focus of our next research steps." (PMID 40133832, 2025). "The effect of SLC7A5 on the malignant phenotype of oxaliplatin-resistant GC cells was verified by CCK-8, EDU, TUNEL, colony formation, wound healing, transwell assay, tumor bearing experiments and WB assay." (PMID 40133832, 2025).
tumor (continued). "MYC up-regulates the expression of solute carrier family 7 member 5 (SLC7A5) and solute carrier family 43 member 1 (SLC43A1), which elevates the uptake of the essential amino acids to promote tumor progression." (PMID 40290126, 2025). "SLC7A5 (LAT1) is also overexpressed in CRC tissue, promoting mTOR activation and tumour aggressiveness, with high expression correlating with poor survival and resistance to EGFR inhibitors." (PMID 41154605, 2025). "Disrupting Gln uptake via SLC1A5, SLC7A5, or SLC38A1 depletion, or by inhibiting GLS, enhances oxidative stress and curtails DNA damage repair, thereby sensitizing tumor cells to ionizing radiation." (PMID 40707944, 2025). "Our study demonstrated that reducing SLC7A5 expression significantly decreased HK2, LDHA, Glut1, and PDK1 levels in HGC27R cells, MKN45R cells, and tumor tissues." (PMID 40133832, 2025). "For instance, solute carrier family 7 member 5 (SLC7A5), a tryptophan transporter belonging to the cationic amino acid transporter, is primarily localized on the plasma membrane of tumor cells." (PMID 41179282, 2025). "In TME, tumor cells preferentially uptake Gln from the microenvironment for energy metabolism through the overexpression of SLC1A5 and SLC7A5 Gln transporters, thereby forcing NK cells into a metabolic crisis." (PMID 40959206, 2025). "Our research elucidates the TME in HNSCC before and after immunotherapy, revealing a novel mechanism by which TP63+ SLC7A5+ HNSCC inhibits ferroptosis and enhances tumor resistance via TP63-induced SLC7A5 upregulation." (PMID 39234254, 2024). "The inhibition of SLC7A5 leads to the enhancement of CD4+ and CD8+ T lymphocytes, thereby boosting the immune response while concurrently diminishing tumor progression and cellular migration." (PMID 38397971, 2024). "This is consistent with the absence of proliferation defects upon KD of the major amino acid transporters (SLC1A5, SLC7A1, SLC7A5 and SLC7A11) in K562 tumours." (PMID 38605144, 2024). "This subpopulation suppresses ferroptosis in malignant cells through the transcriptional upregulation of SLC7A5 mediated by high TP63 expression, thereby promoting tumor growth and resistance to immunotherapy." (PMID 39234254, 2024). "By integrating the mechanistism score with tumor stage, we developed a clinical scoring model based on TP63 and SLC7A5, employing nomograms for the prediction of one-year, three-year, and five-year survival rates in patients." (PMID 39234254, 2024). "A lower level of SLC7A5 was found in the IC0 (immune cells with the lowest expression of PD-L1) and TC0 (tumor cells with the lowest expression of PD-L1) subgroups, as well as in the desert phenotype." (PMID 38790003, 2024). "In an in vivo subcutaneous tumor model, knockdown of IGF2BP2 or SLC7A5 inhibited tumor growth and enhanced the antitumor effects of IR, while co-knockdown of IGF2BP2 and SLC7A5 had the strongest anti-tumor effects." (PMID 38281999, 2024). "In ESCC, circ-SLC7A5, circ-LRP6 and circ-TTC17 have been reported to play tumor-promoting roles, but circFoxo3 and circSMAD7 act tumor-inhibiting roles." (PMID 38514579, 2024). "By analyzing different tumor-infiltrating CD8+ T cell subpopulations, we found reduced expression of both MYC and SLC7A5 in memory-like CD8+ TILs, which is in line with our in vitro findings." (PMID 36717749, 2023). "The downregulated genes (DEPTOR, DPEP1, NAT8, and SUSD2) in the tumor and thrombus were associated with a worse survival rate when the gene was less expressed in the tumor, and the same correlation was observed for the upregulated genes (PLOD2 and SLC7A5)." (PMID 37328520, 2023). "Examination of TCGA dataset of LUAD revealed that SLC7A5 and QPRT are both significantly upregulated in the tumor tissues compared with the normal tissues." (PMID 37095081, 2023).